POU5F2 (POU domain class 5, transcription factor 2)
Description:
Transcription factor that binds preferentially to the octamer motif (5'-ATGTTAAT-3'). May exert a regulatory function in meiotic events that are required for terminal differentiation of male germ cell (By similarity).
Synonyms: SPRM-1; FLJ25680
Tractability: No criterion of Open Targets' tractability assessment is met for any kind of drug.
Gene: Protein-coding gene on chromosome 5 (93,733,220 to 93,741,600, reverse strand). Ensembl gene ENSG00000248483.
Subcellular location: Nucleus
Subcellular location (Human Protein Atlas): Nucleoplasm
Gene Ontology:
Molecular function: protein binding; DNA-binding transcription factor activity, RNA polymerase II-specific; RNA polymerase II cis-regulatory region sequence-specific DNA binding; DNA binding; DNA-binding transcription factor activity
Biological process: regulation of transcription by RNA polymerase II; regulation of DNA-templated transcription
Cellular component: chromatin; RNA polymerase II transcription regulator complex; nucleus
Genetic constraint (gnomAD): Loss-of-function variants: 0 observed, 0.0866 expected, observed/expected ratio (o/e) 0, 90% interval 0 to 1.89. That is too few expected variants to judge how well the gene tolerates losing a copy. Missense variants: 401 observed, 446.79 expected, observed/expected ratio (o/e) 0.9, 90% interval 0.83 to 0.98. Synonymous variants: 191 observed, 187.41 expected, observed/expected ratio (o/e) 1.02, 90% interval 0.9 to 1.15.
Homologues: Orthologues: mouse Pou5f2 (66% identical), Drosophila melanogaster vvl (32% identical), zebrafish pou5f3 (31% identical), zebrafish pou3f1 (29% identical), tropical clawed frog pou3f1 (27% identical), Caenorhabditis elegans ceh-18 (26% identical), zebrafish pou4f4 (23% identical), tropical clawed frog pou4f4 (22% identical), Drosophila melanogaster acj6 (20% identical), Caenorhabditis elegans unc-86 (19% identical). Paralogues in human: POU5F1 (45% identical), POU5F1B (43% identical), POU3F4 (31% identical), POU3F3 (31% identical), POU3F2 (29% identical), POU3F1 (27% identical), POU2F1 (27% identical), POU2F2 (26% identical), POU2F3 (26% identical), POU6F1 (24% identical), POU1F1 (23% identical), POU4F3 (23% identical), and 5 more.